APOE (apolipoprotein E)
Diseases named in the same sentence as APOE in open-access papers (continued):
Sharing a sentence is not in itself a finding about the gene and the disease.
atherosclerosis (continued). "Thus, the deficiency of miR155 in ApoE-/- background leads to increased obesity, increased non-alcoholic fatty liver disease (NAFLD), decreased atherosclerosis, no insulin resistance and no type II diabetes mellitus (T2DM)." (PMID 33488632, 2020). "Thrombotic occlusion rarely occurs in the coronary arteries of ApoE−/− mice, unlike in humans, making it more difficult to extrapolate findings into the clinic, as the effect of atherosclerosis on MI could be different to that which occurs in humans." (PMID 33258000, 2020). "Constant light exposure exacerbated atherosclerosis in male, but not female, ApoE−/− mice." (PMID 32555251, 2020). "Finally, we treated Apoe–/– mice with established atherosclerosis in analogy to the feeding study in APOE*3-Leiden.CETP mice comparing LCD with and without supplementation of 0.01% atorvastatin." (PMID 33296022, 2020). "Consequently, mice lacking ApoE can be used as an animal model of hyperlipidemia (especially hypercholesterolemia) and resulting atherosclerosis, which can be accelerated by feeding a high-fat (western-type) diet." (PMID 33255872, 2020). "In the same way, ApoE-/- mice subjected to atherosclerosis, showed a lack of IL-1β smaller lesions." (PMID 32545788, 2020). "Also, the observed increased atherosclerotic plaque formation and more numerous neutrophils, Ly6Chigh monocytes, and macrophages inside plaques of ApoE−/−Svep1+/− compared to ApoE−/−Svep1+/+ mice accord with the downstream effects of CXCL1 and E-selectin in atherosclerosis." (PMID 33185739, 2020). "Thus, skeletal muscle-specific overexpression of PGC-1α suppressed atherosclerosis progression in ApoE-KO mice without increasing spontaneous activity." (PMID 30858489, 2019). "In summary, ApoE-deficient mice immunized with collagen α1α2(IV)-PADRE responded with a strong Th2 immune response, measured by IgG1 antibody levels, but did not have an effect on atherosclerosis." (PMID 30979943, 2019). "Here, we aimed to characterize the vascular effects of PCSK9 inhibition in APOE*3Leiden.cholesteryl ester transfer protein (CETP) mice, a mouse model for familial dysbetalipoproteinemia with human-like lipoprotein metabolism, on atherosclerosis development, inflammation and EPC and CAC number." (PMID 31366894, 2019). "In the present work, we have shown that a known autophagy inducer—trehalose—given orally for a 16-week period and without any visible adverse effects, inhibited atherosclerosis and attenuated hepatic steatosis in apoE−/− mice fed with a chow and a high-fat diet, respectively." (PMID 30925684, 2019). "Therefore, in addition to atherosclerosis the pathogenesis of diseases such as AMD and DDD could be related to the FH and apoE-macrophage interactions." (PMID 30519244, 2018). "To investigate the effect of hyperglycemia on atherosclerosis and coronary heart disease, we used a mouse model of diet-induced coronary artery atherosclerosis and myocardial infarction, the high fat/high cholesterol (HFC) diet fed SR-B1 knockout (KO)/apoE-hypomorphic (HypoE) mouse." (PMID 30356742, 2018). "Here, we used the same paramagnetic micelles for in vivo non-invasive visualization of EMMPRIN in atherosclerotic apoE and NO3/apoE double null mice, to evaluate the hypothesis that targeted inhibition of EMMPRIN may represent a new mechanism elicited by NO against atherosclerosis." (PMID 30347750, 2018).
atherosclerosis (continued). "Similarly, drinking water supplemented with green tea extract attenuated the development of atherosclerosis without changing the plasma TC or TG level in ApoE-/- mice." (PMID 29593532, 2018). "Adoptive transfer of telomerase reverse transcriptase–/– Tregs into Rag2–/– ApoE–/– (recombination activating gene 2/apolipoprotein E) double knockout mice demonstrated that telomerase function was not required for the ability of Tregs to protect against atherosclerosis." (PMID 29599138, 2018). "Therefore, some, but not all, of the findings from complicated regions of human plaques were also observed in atherosclerosis plaques from BATIRKO; ApoE−/− mice: decreased IRA/IRB ratio, increasing trend of IGF-IIR and reduced VSMC content with an increase of apoptotic cells." (PMID 29463262, 2018). "Furthermore, decreased insulin signaling in non-hematopoietic cells, as achieved by transplantation of ApoE−/− mouse model of atherosclerosis with bone marrow cells from IRS1+/− IR+/− ApoE−/− mice, contributed to increased atherogenesis in these mice." (PMID 28752048, 2017). "While a lack of APOE and RCT might play a pathogenic role due to reduced efficacy of cholesterol and β-amyloid clearance in atherosclerosis and Alzheimer disease, excessive APOE and RCT might be responsible for IIRC activation and chronic inflammation in AMD." (PMID 29270905, 2017). "Furthermore, decreased insulin signalling in nonhaematopoietic cells, as achieved by transplantation of ApoE−/− mouse model of atherosclerosis with bone marrow cells from IRS1+/− IR+/− ApoE−/− mice, contributed to increased atherogenesis in these mice." (PMID 28899902, 2017). "As the severity of atherosclerosis is related with the amount of inflammation or lipids in the serum, we first determined the levels of bio-metabolic factors such as triglyceride (TAG), low-density lipoprotein (LDL)-cholesterol and total cholesterol in the blood sera of ApoE-KO mice." (PMID 28241014, 2017). "In conclusion, this study establishes that dietary SM does not affect circulating SM levels or increase atherosclerosis in mice that are maintained on a high fat diet, but that it is anti-atherogenic in chow-fed apoE-/- mice, possibly due to SM-mediated alterations in gut flora." (PMID 29240800, 2017). "Analysis of H&E- and Oil Red O-stained histological sections of the aortic sinus revealed that atherosclerotic lesions and lipid content were significantly higher in the HFD group (p < 0.05) than in the NOR group, suggesting that the HFD successfully induced atherosclerosis in ApoE (-/-) mice." (PMID 28536634, 2017). "Additionally, genetically atherosclerosis-prone mice lacking apolipoprotein E showed changes in DNA methylation in peripheral blood leukocytes, which contributed to dysregulation of inflammation and promotion of atherosclerosis." (PMID 27724854, 2016). "It remains unknown regarding the precise role of TRPV4 in mouse and human atherosclerosis and whether endothelial function and atherosclerosis development will be exaggerated in TRPV4−/−; ApoE−/− mice, or in ApoE−/− mice treated with the TRPV4 inhibitor GSK2193874." (PMID 27191895, 2016). "The observation that individuals with very low or completely absent circulating ApoE develop early atherosclerosis, and that this has a genetic basis, has been influential in the development of hypotheses on the role of ApoE in atherosclerosis." (PMID 27755538, 2016). "Similarly, in hyperlipidemic ApoE‐deficient mice, deletion of either CD36 or SR‐A1 significantly reduces lipid accumulation in macrophages, but does not diminish atherosclerosis." (PMID 26493158, 2016).
atherosclerosis (continued). "Moreover, deletion of the tumor suppressor p19(ARF) in ApoE−/− mice reduces apoptosis in plaque macrophages and VSMCs and aggravates atherosclerosis, though the effect on plaque necrosis was not examined." (PMID 27847551, 2016). "Similarly, sub-chronic exposure studies in animals have shown that apolipoprotein E (ApoE) null mice exposed to PM at ambient levels, concentrated PM2.5, ultrafine particles (UFP), and diesel exhaust emissions, show accelerated atherosclerosis." (PMID 27221567, 2016). "Due to the fact that ApoE −/− mice fed a HFD show reduced SIRT6 expression, it is of great importance to investigate in future studies whether EC-specific SIRT6 overexpression will rescue vascular inflammation and atherosclerosis development." (PMID 27249230, 2016). "ApoE-deficient mice lacking protein kinase ATM (ataxia telangiectasia mutated), a protein pivotal in DNA damage detection, showed accelerated development of atherosclerosis." (PMID 27213333, 2016). "P-selectin appears to be a key adhesion receptor mediating the recruitment of monocytes/macrophages into the lesions and promoting advanced atherosclerosis in ApoE−/− mice, with earlier and more advanced lesions in mice lacking ApoE alone in comparison with double-knockout ApoE/P-selectin mice." (PMID 27618031, 2016). "However, because many molecules (e.g., ApoE, thrombospondin, protein C, tPA, thrombin) are also ligands of LRP, the biological consequences of HNP and LRP binding remain to be investigated in the pathogenesis of atherosclerosis." (PMID 27430968, 2016). "However, an in vivo study in apoE-null mice showed that TRAIL could promote apoptosis in the plaque by binding to decoy receptors, thus slowing the progression of atherosclerosis." (PMID 26334877, 2015). "To test the hypothesis, we used a CUMS model in apoE-/- mice to investigate the effects of TLR4 small interfering RNA (siRNA) and a specific NF-κB antagonist pyrrolidine dithiocarbamate (PDTC) on stress-induced inflammation and atherosclerosis." (PMID 25860573, 2015). "Interestingly, accelerated lesion formation in apoE-/-VDR-/- mice was not correlated with serum lipid levels, known to be the major risk factor for atherosclerosis." (PMID 26322890, 2015). "We demonstrated that in apoE−/− mice fed a Western diet, hepatic high-level expression of hMsrA reduces plasma VLDL/LDL, improves HDL function and redox status, and suppresses liver and plasma inflammation, resulting in diminished hepatic steatosis and attenuated atherosclerosis." (PMID 26318157, 2015). "To investigate the influence of xyloketal B on atherosclerosis, we fed apoE−/− mice with high-fat diet with or without xyloketal B/simvastatin treatment for 16 weeks, and then evaluated the atherosclerotic lesion area in the aortic arch, thoracic and abdominal aorta." (PMID 25874925, 2015). "Exercise in APOE-lacking mice may attenuate the development of atherosclerosis in the periphery, and these effects may be due to exercise-induced enhancement of anti-inflammatory cytokines." (PMID 24795624, 2014). "In this present study, we show that oral administration of human therapeutic doses of cetirizine (1 mg/kg b.w) or fexofenadine (10 mg/kg b.w) in ApoE−/− mice for three months did not reduce progression of atherosclerosis, instead, increased the atherosclerotic lesion formation." (PMID 25020133, 2014).
atherosclerosis (continued). "In this study, we examined how exposure to two pathogens associated with atherosclerosis induces modulation of gene expression in aortic tissues using ApoE-/- mice that spontaneously develop atherosclerosis in the absence of an additional pro-atherogenic stimulus." (PMID 25540039, 2014). "Although the apoE−/− mice model has been used extensively in experiments studying atherosclerosis as it gives the opportunity to study genetic influence on atherosclerosis without using a high-fat diet rich in cholesterol, it is also a challenging model to use." (PMID 24840793, 2014). "However, there were more CD68-positive macrophages and ICAM-1-expressing cells in plaques from apoE−/−/PGC-1α−/− mice compared to those from littermate controls, implicating a potential role of macrophage PGC-1α in atherosclerosis in vivo which is in keeping with the data presented above." (PMID 23964012, 2013). "In parallel, oxidative stress and DNA damage in bone marrow mononuclear cells (MNC), which are physiologically involved in tissue repair and have therapeutic vascular effects in hypercholesterolemia and atherosclerosis, have not yet been investigated in the apoE−/− mouse model." (PMID 23385237, 2013). "Moreover, in 5/6 nephrectomized ApoE-deficient mice, INT-747 reduces chronic kidney disease (CKD)-induced vascular calcification independent of atherosclerosis progression." (PMID 23593273, 2013). "In addition, chronic treatment with bone marrow derived progenitor cells from young non-atherosclerotic apolipoprotein E knock-out (ApoE-/-) mice prevents atherosclerosis from progression in ApoE-/- recipients." (PMID 25984328, 2013). "However, Bjorkbacka et al9 showed that deletion of CD14 had no impact on aortic root atherosclerosis in apoE−/− mice." (PMID 23537804, 2013). "However, a recent study also found that genetically crossing APOE mice to mice that lack NLRP3 does not diminish the severity or incidence of atherosclerosis." (PMID 23087690, 2012). "However LDL immunization was effective against atherosclerosis even in CD4/apoE double knockout mice, suggesting CD4+ T cells are not important mediators of the beneficial effect of LDL immunization." (PMID 22347402, 2012). "However, the formation of large and advanced plaques is not sufficient to trigger ATLO formation as atherosclerosis in ApoE−/− mice begins and is most advanced in the aortic arch where ATLOs can only rarely be observed." (PMID 22783198, 2012). "Finally, we demonstrate that a 26-fold difference in macrophage-derived apoE expression and its accumulation in atheroma are not proportionally effective in regulating the progression and complexity of advanced atherosclerosis." (PMID 22606237, 2012). "In addition, RAGE inactivation also inhibited atherosclerosis through blocking the RAGE-mediated inflammatory reactions and oxidative stress in nondiabetic models with atherosclerosis of ApoE-KO and low-density lipoprotein (LDL) receptor KO mice." (PMID 22110482, 2012). "Moreover, introduction of a PF4 null locus, into the ApoE-/- mouse, a well known model of atherosclerosis reduced atherosclerotic lesion formation compared with control mice, thus demonstrating the important role of PF4 in the pathogenesis of atherosclerosis." (PMID 22792197, 2012). "Our results show that specific ablation of p38α in macrophages or endothelial cells did not affect the development of atherosclerotic plaques in ApoE−/− mice, suggesting that p38α activity in these cell types does not play a crucial role for the pathogenesis of atherosclerosis." (PMID 21695272, 2011). "Indeed, after 6 month of normal diet, atherosclerosis was relatively advanced in the absence of L-sel, while plaque burden was still low in the ApoE−/− control group and comparable to the ApoE−/− control animals after 6 weeks of HCD." (PMID 21760899, 2011).
atherosclerosis (continued). "Furthermore, deficiency of CCR5 (the receptor for CCL5, a chemokine also known as RANTES) in ApoE-/- mice does not appear to be protective in the early stages of atherosclerosis." (PMID 21526997, 2011). "We found that MNC therapy in apoE KO mice resulted in a marked decrease in O2·- production and a concomitant upregulation of eNOS in the aorta, supporting the idea that another important mechanism by which MNC therapy attenuates the progression of atherosclerosis is by relieving oxidative stress." (PMID 21896159, 2011). "Thus, our results demonstrate that macrophage p38α deficiency did not affect the development of atherosclerotic plaques in the ApoE−/− mouse model, suggesting that macrophage p38α does not have an important role in the pathogenesis of atherosclerosis." (PMID 21695272, 2011). "Thus, our results show that endothelial cell-specific ablation of p38α does not affect the development of atherosclerosis in the ApoE−/− model of the disease." (PMID 21695272, 2011). "A previous study demonstrated that the absence of CD36 on macrophages may protect against atherosclerosis in ApoE-/- mice, strongly supporting a pro-atherogenic role for CD36." (PMID 21486455, 2011). "However, our in vivo experiments showed that endothelial cell-specific ablation of p38α did not affect the development of atherosclerosis in ApoE−/− mice, as assessed by measurement of lesion size, macrophage and collagen content and necrotic core area." (PMID 21695272, 2011). "However, bone marrow transplantation from C3H/HeJ to Apolipoprotein E (ApoE)−/−, did not alter atherosclerosis development." (PMID 20652007, 2010). "Thus it may be speculated that increased vesl-2 protein in ApoE+/−-TLR2+/+ mice fed a high fat diet and injected with P. g may lead to an increase in intracellular calcium, contributing to the increased atherosclerosis in this group of mice." (PMID 18787704, 2008). "One of the aims of the present study was to compare vascular TNF-α and TNF receptor expression in a mouse strain that spontaneously develops atherosclerosis (apoE-/-/LDL receptor-/- mice) with control mice that does not develop atherosclerosis unless challenged with a high-fat diet (C57BL/6)." (PMID 23675033, 2007). "Fibrinogen knockout mice against an apoE-/- background did not have fewer arterial lesions ranging from early lesions to complex fibrous plaques, suggesting that fibrinogen is not an essential molecule for atherosclerosis." (PMID 15574198, 2004). "In addition, compared with ApoE−/− mice that do not engage in exercise, the ApoE−/− mice with 12 weeks of swimming exercise have significantly lower resistin levels in the aorta, less endothelial damage and reduced the severity of atherosclerosis." (PMID 40861271, 2025). "The literature suggested FCGR3A(CD16A) + monocytes were significantly increased in apoE-/- mice with high fat diet, which might correlate with aortic MMP-9 mRNA expression and serum TNF-α level, indicaitng FCGR3A involved in the progression of atherosclerosis through inflammatory pathways." (PMID 41348730, 2025). "TCRγ−/−/ApoE−/− mice fed a western diet or a normal diet for 10 weeks demonstrated no change in atherosclerotic plaque size compared to control mice indicating that γδ T cells may not be involved in atherosclerosis." (PMID 37681883, 2023). "Although APOE cannot cross the BBB, the APOE in peripheral circulation could regulate brain function either by directly acting on the endothelial cells of the BBB or by indirectly regulating endothelial and neuronal functions through lipid metabolism, atherosclerosis, and peripheral inflammation." (PMID 37686334, 2023). "However, SET7-dependent trained immunity (innate immune memory) and itaconate-dependent trained tolerance maintained a consistent level throughout the ApoE–/– HFD atherosclerosis time course, rather than being diminished by the disappearance at 6 weeks innate immune pathway." (PMID 38327764, 2023).